CCL5 (C-C motif chemokine ligand 5)
Diseases named in the same sentence as CCL5 in open-access papers (continued):
Sharing a sentence is not in itself a finding about the gene and the disease.
tumor (continued). "First, the role of CCL5 in CRC staging (early/late-stage) may be different; second, high expression of CCL5 in blood and tumor sites, respectively, may have different diagnostic implications." (PMID 36387070, 2022). "However, deletion of CCL5 in BM precursors was shown to arrest tumor-associated macrophage differentiation and induce robust anti-tumor immunities." (PMID 36430701, 2022). "As a receptor encoding CCL5, it can promote tumorigenesis, matrix formation, and tumor development." (PMID 35296026, 2022). "Regarding the tumors, it has been well studied that CXCL9/10/11 (ligands for CXCR3) produced by macrophages and DCs, along with CCL5 (ligands for CCR5) secreted by tumor cells, are associated with T cell recruitment to the TME and a favorable response to chemotherapy and immunotherapy." (PMID 35925680, 2022). "CCL5 is also associated with T-cell infiltration and tumor control in other carcinomas." (PMID 35131874, 2022). "Additionally, it was also reported that reduction of CCL5 expression caused tumor-infiltrating lymphocyte (TIL) desertification and forced CCL5 expression prevent TIL loss in vivo." (PMID 34899325, 2021). "Biglycan has been demonstrated to trigger the synthesis of the macrophage chemoattractants chemokine (C-C motif) ligand CCL2 and CCL5; thus, it may be possible that biglycan deficiency modulates tumor vasculature through recruitment of macrophages." (PMID 33966638, 2021). "Moreover, CCL-5 deficiency has been shown to increase tumor infiltrating CD8+ T cells in the context of CRC." (PMID 34611474, 2021). "Additionally, CCL5 inhibition has been shown to limit monocyte recruitment and reprograming to immunosuppressive tumor-associated macrophages." (PMID 34030676, 2021). "This raises the possibility that combination therapies that deplete Tregs or tumor-associated macrophages may enhance the anti-tumor effect of CCL5 administration in some contexts." (PMID 34030676, 2021). "Alternatively, therapies that select for anti-tumorigenic potential of these cell types, such as the effect anti-PD-L1 may have on tumor-associated macrophages, may also enhance the anti-tumor effect of CCL5." (PMID 34030676, 2021). "The mechanisms underlying CCL5 elevation in the tumor microenvironment are increasingly clear." (PMID 32425930, 2020). "To our surprise, we also found CCL5 and CXCL13 had the highest expression levels in tumor-associated T cells, which indicates that CCL5 and CXCL13 may play important roles in tumor immunity." (PMID 32549766, 2020). "Both CCL2 and CCL5 mediate the infiltration of tumour-associated macrophages and inhibit potential anti-tumour T-cell activities, thereby controlling the populations of leukocytes at tumour sites." (PMID 33046030, 2020). "CCL5 (chemokine ligand 5) is chemotactic for T cells, eosinophils, and basophils, and it activates immune cells (including specific NK cells), thereby exerting anti-tumor immunity or immune surveillance; however, several studies have reported that CCL5 is associated with cancer progression." (PMID 32513298, 2020). "CCL5 not only affects cancer cells but also tumor-associated cells." (PMID 33076281, 2020). "MSC/fibroblast-derived chemokines, including murine CXCL1 and CXCL2 (counterparts of human CXCL8), CCL2 and CCL5 were associated with recruitment of neutrophils, tumor-associated macrophages and myeloid-derived suppressor cells to TNBC tumors, where they promoted disease course." (PMID 31031757, 2019). "Elevated levels of CCL5 are associated with tumor progression in different cancers." (PMID 30867568, 2019). "Moreover, the expression of the tumor-promoting cytokines IL-6, which has been shown to be regulated by IL-17C in different disease models, and CCL5 was decreased in lungs of IL-17C deficient Kras mice." (PMID 31316109, 2019). "The results showed that CCL5-deficiency could delay both tumor growth and metastasis of CT26 in orthotopic CRC model." (PMID 29991744, 2018).
tumor (continued). "The decreased secretion of IFN-γ and CCL5 in Med23-deficient iNKT cells after α-GalCer administration may be one of the main reasons for their impaired anti-tumor ability." (PMID 30250136, 2018). "Rosner and colleagues demonstrated that RKIP over-expression in metastatic TNBC mouse models robustly blocks recruitment of tumor-associated macrophages (TAMs) into the tumors through a mechanism dependent upon the chemokine CCL5 (C-C motif chemokine ligand 5)." (PMID 30181452, 2018). "Furthermore, this appears to be ancestry-related, as SNPs in CCL2 and CCL5, which are associated with macrophage recruitment to the tumor, were associated with tumors of AA women and increased in AA QNBC patients." (PMID 29912871, 2018). "CCL5 is, indeed, implicated in bidirectional communication patterns between cancerous and normal breast cells as it can be secreted either by tumor or mesenchymal cells that are recruited to the tumor." (PMID 30513833, 2018). "Collectively, CCL5-deficiency inhibits tumor growth and metastasis of CRC in mouse models." (PMID 29991744, 2018). "We firstly showed that CCL5-deficiency in the tumor microenvironment could significantly downregulate the expression level of S100a9 in CD11bhiS100a9hi TAMs in CRC." (PMID 29991744, 2018). "CCL5 in particular has been linked with tumour cell proliferation and metastasis." (PMID 27845732, 2016). "While CCL5 may promote efficient anti-tumour immune responses, it has also been associated with cancer progression and metastasis." (PMID 27335323, 2016). "Therefore, we suggest that CCL5 promotes VEGF-C-dependent tumor-associated lymphangiogenesis by down-regulating miR-507 in vivo." (PMID 27166194, 2016). "In addition, the interaction between CCR5 and its ligand, CCL5, recruits Tregs and tumor-associated macrophages as well as increases the generation of MDSCs." (PMID 27340784, 2016). "IL-1β and TNF-α may alter stromal cells enhancing the expression of CCL2, CXCL8, and CCL5 by cancer-associated fibroblast and mesenchymal stem cells in the inflammatory tumor microenvironment of breast cancer." (PMID 27886105, 2016). "Downregulation of the Ccl2 and Ccl5 genes associated with this pathway may preclude efficient recruitment of various immune effectors into tumors or tumor-bearing tissue." (PMID 26441959, 2015). "Our findings that FAK regulated the transcription of cytokines and chemokines (including Ccl5 and TGFβ2) that were associated with elevated intra-tumoral Tregs and tumor tolerance led us to consider a possible role for nuclear FAK in regulating the transcription of these genes." (PMID 26406376, 2015). "In tumor lesions, the local expression of CCL5 and CXCL10 was positively associated with the expression of the CD8+ T lymphocyte markers CD8 and Granzyme B (RCD8 = 0.2338, pCD8 < 0.01, RGranB = 0.5517, pGranB < 0.001; RCD8 = 0.2972, pCD8 < 0.005, RGranB = 0.3204, pGranB < 0.001)." (PMID 26317795, 2015). "CCL5 localizes with tumor-infiltrating leukocytes, and CCL5 concentration may be associated with CD8+ T cell infiltration." (PMID 15969748, 2005). "We next evaluated whether the tumor growth inhibition observed in Ackr2-targeted B16-F10 cells is associated with changes in immune cell infiltration, likely driven by altered availability of key chemokines such as CCL5 and CXCL10." (PMID 40248897, 2025). "Furthermore, CCL5 positivity in TCs was associated with a 1.55-fold, 1.81-fold, 1.65-fold, and 2.60-fold increased risk of tumor-associated death for patients with tumor stage pT3 + 4, nodal stage N0, patients without chemotherapy or tumors of the luminal molecular subtype, respectively." (PMID 38928033, 2024). "Indeed, CXCL16 and CCL5 have already been shown to be associated with increased activity and infiltration of T cells and NK cells to different sites, further supporting the notion that these molecules directly affect anti-tumor immunity." (PMID 36646904, 2023).
tumor (continued). "However, a role for this virus in GBM treatment is precluded as GM-CSF may be a pro-tumor factor through activation of CCL5 in GBM-associated macrophages." (PMID 35795092, 2022). "Therefore, our study provides evidences indicating that CCL5 may serve as a potential diagnostic marker and therapeutic target for tumor budding in CRC." (PMID 35241150, 2022). "Therefore, CCL5 may serve as a potential diagnostic marker and therapeutic target for tumor budding in CRC." (PMID 35241150, 2022). "However, acetylated SNAI1 can act as an activator to induce tumor necrosis factor alpha (TNF-α), C-C motif chemokine ligand 2 (CCL2), and C-C motif chemokine ligand 5 (CCL5) gene transcription, which in turn promote carcinoma progression and the recruitment of tumor-associated macrophages (TAMs)." (PMID 34298613, 2021). "Since NK cells, which are important anti-tumor effectors, were preferentially recruited into the tumors of inflammasome-deficient mice, and since increased levels of CCL5 within the tumor microenvironment were detected, we tested whether NK cells were responsible for the reduction in tumor growth." (PMID 33042810, 2020). "After MSC recruitment by tumors, pro tumor effects could be linked to RANTES (CCL5)." (PMID 29494553, 2018). "After MSC recruitment by the tumor, an MSC pro tumor effect could be linked to RANTES (CCL5)." (PMID 29494553, 2018). "Since it is possible that attenuated Ccl5 expression alters the functional status of tumor-associated macrophages/microglia, current studies are focused on identifying potential changes in the tumor microenvironment conferred by reduced glioblastoma tumor cell Ccl5 production in vivo." (PMID 28380429, 2017). "Research shows that malignant T cells can recruit CCR1-expressing myeloid immune cells to the tumor site by secreting CCL5 and CCL23." (PMID 41614909, 2026). "Mechanistically, tumor-infiltrating CAR-T cells play a dual role: they release antitumor effector molecules (e.g., IFN-γ, TNF-α), but also produce CCL5, which promotes tumor growth by inducing VEGF and angiogenesis." (PMID 42089445, 2026). "A comprehensive assessment of the post-treatment tumor microenvironment revealed that KRAS degradation increased tumor-derived CCL5 levels, thereby promoting CD8+ T-cell recruitment and amplifying antitumor responses." (PMID 41944287, 2026). "Pretreatment with a CCL5 neutralizing antibody suppressed CD8+ cell infiltration into the tumor, eliminating the antitumor effect." (PMID 42022218, 2026). "Here, we identify a tumor-stromal interaction mediated by the CCL5/CCR5 axis that drives cisplatin resistance in NEPC." (PMID 41152972, 2025). "Pan-cancer analysis showed that IL18 and CCL5 proteins were overexpressed in GBM compared with other tumor types." (PMID 41155216, 2025). "To explore the detailed mechanisms that mediate the activation of CD8+ T cells, we analyzed the drug combinations treated tumor tissues and found tumor microenvironment was reshaped through CCL5 mediated CD8+ T cell recruitment." (PMID 41281743, 2025). "Taken together, these results suggested the NOD1/NF-κB pathway was involved in the secretion of CCL5 from tumor cells activated by L. intestinalis." (PMID 39773173, 2025). "Increased levels of the Th1 chemokines C-C motif chemokine ligand 5 (CCL5), CXC-chemokine ligand 9 (CXCL9) and CXCL10 are associated with increased numbers of tumor-infiltrating CD8+ T cells." (PMID 40959109, 2025). "Blocking tumor β8 or its CCL5 signaling partially reverses macrophage polarization and inhibits tumor progression." (PMID 41451227, 2025). "In our investigation, we found that L. intestinalis enhanced tumor cell-derived CCL5 secretion to eliminate tumors." (PMID 39773173, 2025). "VB-85247 also induced the IFN-dependent chemokines CXCL10 (IP-10) and CCL5, which are known to be important for the recruitment of immune effector cells into the tumor microenvironment." (PMID 39700406, 2025).
tumor (continued). "Subsequently, at the Post‐NT state, these cells displayed increased synthesis of T‐cell suppressive factors such as Tnfaip3, Ccl5 and Ctla4,89, 90, 91 coinciding with tumour emergence." (PMID 40887856, 2025). "Leronlimab reduced circulating tumor-associated cells and modulated CCR5-related cytokine production (CCL5, IL-6, and TNF-α), highlighting the potential of CCR5 blockade to reprogram the immunosuppressive microenvironment." (PMID 40868199, 2025). "Mast cells with low BTG2 expression have enhanced migratory capacity and are preferentially recruited to lymph nodes by cytokines such as CCL5, secreted by tumor cells during metastasis." (PMID 40313959, 2025). "Particularly noteworthy is the robust positive correlation between TIGD1 and HMGB1 expression across nearly all tumor types, along with significant associations with ICAM1, CCL5, and TNFRSF18 in the majority of cancers." (PMID 40565566, 2025). "In contrast, under cisplatin treatment, tumors from CCL5 knockout mice showed decreased proliferation and increased apoptosis compared with those from controls, highlighting the essential role of CCL5 in the tumor microenvironment during cisplatin treatment." (PMID 41152972, 2025). "Our findings provided evidence that L. intestinalis induced tumor cells to secrete CCL5, thereby facilitating the chemotaxis of DC and suppressing the tumorigenesis." (PMID 39773173, 2025). "OVs effectively promote T-cell infiltration into the TME through genetic engineering to express chemokines (e.g., CXCL10, CCL5) or by disrupting physical tumor barriers, thereby enhancing anti-tumor immune responses." (PMID 41425703, 2025). "Western blotting and ELISA confirmed that the protein levels of Cxcr6 and Ccl5 were also significantly elevated in tumours from the PR + IRT and FRA + IRT groups." (PMID 40715695, 2025). "These T cells also recruit antitumor macrophages to the tumor microenvironment via CCL5/4-CCR5 and CCL3/CCL3L3-CCR1 signaling interactions." (PMID 41203637, 2025). "The analysis revealed that CCL4 (p = 0.0076) and CCL5 (p = 0.0347) expression levels tended to decrease as the tumor progressed." (PMID 39859340, 2025). "Given that tumor cell‐expressed CCL5 is essential for T cell infiltration, we wondered to examine the contribution of T cells to the tumor‐suppressive effect of KMT5C knockdown in NSCLC." (PMID 40126333, 2025). "Arming OVs with the ability to produce chemokines, such as chemotactic cytokine CCL5, increases the recruitment of anti-tumor CD8+ T cells and NK cells, which express the receptor for CCL5, CCR5." (PMID 39857692, 2025). "NLRP4-eco exerted tumor-suppression capacity through chemokine reprogramming including CCL5 and CXCL2." (PMID 40087771, 2025). "Because CCL3, CCL4, and CCL5 signal through the CCR5 receptor, we next evaluated LLC tumor growth in CD8+ T cell–sufficient and –deficient mice treated with the FDA-approved CCR5 antagonist, maraviroc." (PMID 40553564, 2025). "The CCL5/CCR5 axis promotes tumour growth, ECM degradation, and cancer cell migration, while CCR5+ cancer cells exhibit stem-like properties, contributing to therapy resistance." (PMID 40361472, 2025). "The overexpression of 12‐LOX results in the polarization of THP‐1+ macrophages toward an immunosuppressive M2 macrophage phenotype through the expression of the chemokine CCL5, ultimately leading to tumor radioresistance." (PMID 41346571, 2025). "CCL22 and CCL5 are key chemokines within the tumor TME that participate in immune evasion by recruiting immunosuppressive cells." (PMID 40739089, 2025). "As such, interruption of these interdependent nodes resulted in inhibition of paracrine factors that attract T cells (Ccl2, Ccl3) and those important for TAM support of tumor growth (Ccl4, Ccl5)." (PMID 41497446, 2025).
tumor (continued). "The infiltration of T cells is inhibited by Wnt pathway activation and secreted chemokines CCL4 and CCL5, facilitating tumor growth in melanoma, lung, and colon cancer." (PMID 40647402, 2025). "The role of CCL5 in tumor-stromal crosstalk was investigated using immunofluorescence, ELISA assays, co-culture assays, and CCL5 knockout mice." (PMID 41152972, 2025). "This synergy indicates a robust anti-tumor immune environment driven by both the temporal expression of CCL5 and the active roles of cytotoxic immune cells." (PMID 41301844, 2025). "Produced by tumour cells, lymphocytes, and myeloid cells, CCL5 plays a dual role in immune activation and tumour immune evasion." (PMID 40361472, 2025). "Results showed that CCL5 in tumor tissues was significantly increased in the combo group and further elevated in the combo+CCL5 group." (PMID 40995650, 2025). "CCL5 and CXCL8 also play roles in recruiting monocytes, neutrophils, and other leukocytes, which can differentiate into TAMs and tumor-associated neutrophils (TANs), both of which can assume pro-tumorigenic roles." (PMID 39930476, 2025). "Next, we examined the contribution of CCL5‐mediated T cell infiltration to the tumor‐suppressive effect of KMT5C knockdown." (PMID 40126333, 2025). "The expression of chemokines, such as CCL2, CCL3 and CCL5, in the tumor microenvironment in both human and murine models are associated with enhanced recruitment of myeloid-derived cells including macrophages." (PMID 39566333, 2025). "Mechanically, L. intestinalis ameliorates tumorigenesis by stimulating tumor cells to secrete CCL5 and recruiting DC in the TME by the NOD1/NF-κB signaling pathway." (PMID 39773173, 2025). "Within the tumor microenvironment (TME), tumor-associated macrophages predominantly adopt an M2-like phenotype, secreting cytokines such as IL-10 and TGF-β, chemokines like CCL2 and CCL5, and proteases such as matrix metalloproteinases (MMPs)." (PMID 40487409, 2025). "Target suppression of CCR5, CCL5 or CSF1 or both by knockdown of HIF significantly suppresses primary tumor growth and metastasis." (PMID 40676710, 2025). "This sequestration relieves the miR-214-3p-mediated suppression of the chemokine CCL5, leading to enhanced CCL5 expression and consequently promoting tumor cell adhesion and invasion." (PMID 41357241, 2025). "Research in murine tumor models has shown that cDC1 infiltration depends on NK cells, which release the chemoattractants CCL5 and XCL1." (PMID 40667699, 2025). "An enrichment in the T cell adhesion pathway was further supported by the upregulation of genes regulating T cell chemotaxis and recruitment, including chemokine receptors CXCR4 and CCL5 which enable T cell migration toward tumours." (PMID 41267637, 2025). "MFA also recruits tumor‐associated macrophages through CCL2 and CCL5 signaling, fostering an immunosuppressive niche conducive to metastasis." (PMID 40755324, 2025). "HCMV also encodes pUL21.5, a small peptide that antagonizes the activity of the cytokine CCL5 (RANTES), which, while important in the T-cell response to chronic infection, has been implicated as a pro-inflammatory mediator of tumour progression." (PMID 41194666, 2025). "Elevated concentrations of CCL5 within the tumor microenvironment contribute to immune evasion by recruiting immune cells that promote the survival and migration of cancer cells, thereby heightening the risk of metastasis." (PMID 40076892, 2025). "Mechanistically, L. intestinalis initiated tumor cells to secrete CCL5, a chemotactic factor for DC, through activation of the NOD1/NF-κB signaling pathway." (PMID 39773173, 2025). "CCL5 has the ability to induce the formation of angiogenesis cells, which are necessary for tumor growth, nourishment, and dissemination, and it attracts endothelial cells, the lining cells of blood vessels, to carry out this function." (PMID 40297849, 2025).